EGF (epidermal growth factor)
Diseases named in the same sentence as EGF in open-access papers (continued):
Sharing a sentence is not in itself a finding about the gene and the disease.
tumor (continued). "Thus, in addition to overexpression of the EGF receptor, its ligands epidermal growth factor (EGF), transforming growth factor-α TGF-α, amphiregulin (AR), betacellulin (BTC), heparin-binding EGF-like growth factor (HB-EGF), and epiregulin (EREG) have been reported to be upregulated in tumor tissues." (PMID 31921216, 2019). "Other EGFR ligands that have a lower affinity to EGF, such as TGF-α, HB-EGF, AREG, BTC, and EPGN, may stimulate the growth, invasion, and metastasis due to their dysregulation in cancer, which promotes the higher tumor survival through autocrine or paracrine stimulation." (PMID 30308958, 2018). "EGF may also be involved in reducing docetaxel efficacy in cancer cells; however, a number of other molecules including IL-6, TGFβ, CXCL12, CCL21, VEGF, among others secreted by activated lymphatics are known contributors to drug resistance and these interactions may be tumor cell specific." (PMID 29976154, 2018). "A marker chromosome including EGFR positive homogeneous staining regions (HSR) might serve as EGFR reservoir, enabling tumor cells to regain extrachromosomal EGFR amplification in response to microenvironmental stimuli like discontinued EGFR inhibitor exposure or, possibly, EGF withdrawal." (PMID 28934307, 2017). "Furthermore, transwell analysis showed rMIIP S303A expression significantly inhibited EGF-induced tumor cell invasion, and no additional effects on impaired invasive ability were observed when rMIIP S303A mutant co-expressed with RelA K310R in HCT116 cells compared with its WT counterpart." (PMID 29038521, 2017). "However, the influence of MCT1 on EGF-mediated motility in the absence of an effect on EGFR expression or activation highlights a more general mechanism of MCT1 regulation of growth factor-stimulated tumor cell motility." (PMID 27127175, 2016). "The EGFR ligands: epidermal growth factor (EGF), transforming growth factor-α (TGFA), heparin-binding EGF-like growth factor (HBEGF), amphiregulin (AREG), beta-cellulin (BTC), epiregulin (EREG) and epigen (EPGN), may increase tumor growth, invasion, and metastasis through EGFR activation." (PMID 27669890, 2016). "Within tumor microenvironment, the primary tumors may activate stromal and inflammatory cells leading to the secretion of a lot of metastatic factors including hepatocyte growth factor (HGF), epidermal growth factor (EGF), and transforming growth factor-β (TGFβ)." (PMID 26840563, 2016). "Interestingly, FLOT1 has been reported to be crucial for coordinated assembly of signaling complexes and signal transduction induced by TNF-α, EGF, HGF and IGF-l, suggesting that FLOT1 might play an important role in mediating the heterotypic signals originate in the tumor microenvironment." (PMID 26646322, 2016). "Also, the potential for TIMP-2 to either promote or inhibit cell growth could be affected by the concentration of TIMP-2 and the presence or absence of growth factors such as EGF or PDGF in the tumor microenvironment." (PMID 26556867, 2015). "Within the tumor microenvironment, the primary tumor may interact with stromal and inflammatory cells, leading to the secretion of numerous growth factors and cytokines, including hepatocyte growth factor (HGF), epidermal growth factor (EGF), and transforming growth factor-β." (PMID 25607934, 2015). "In addition several studies have suggested that tumor-derived platelet-derived growth factor (PDGF), epidermal growth factor (EGF), vascular endothelial growth factor (VEGF), and interleukin-6 (IL-6) may be required for localization, integration and/or survival in tumors." (PMID 23744479, 2013). "Importantly, the tumor cells used in this study are known to be nonmetastatic under all conditions; nevertheless, they have acquired high metastasizing abilities in vivo in mice, following a brief stimulation by TNFα + Estrogen + EGF." (PMID 24369447, 2013).
tumor (continued). "Furthermore, the overlap of EGF and IGF-2 pathways, as demonstrated by merging both networks into a single pathway, could enable IGF-2 to take over the functional role of EGF and thus render the tumor cell independent of EGF signaling." (PMID 21464922, 2011). "However, we show that: 1) BALF EGF levels are very low and do not differ between naïve and tumor-bearing lungs; 2) macrophages produce trace amounts of EGF in vitro; and 3) EGF does not stimulate neoplastic lung proliferation either alone or in combination with IGF-1 or MØCM (7 and data not shown)." (PMID 21699731, 2011). "In addition, our data indicate that in HC11 cells PI-3-kinase regulated the EGF-dependent transcription of cyclin D1 and osteopontin (OPN) (Wang, Galbaugh, and Cutler, unpublished observation), both of which are regulated by the PI-3-kinase pathway in tumor cells." (PMID 16984645, 2006). "Using two model systems we have shown that PCNA is induced in non-cycling cells by adjacent transplanted tumour cells and that this phenomenon may be mimicked by the in vivo administration of growth factors (transforming growth factor alpha and epidermal growth factor)." (PMID 7914422, 1994). "Fractionation of tumour extracts by either ion-exchange chromatography or gel filtration revealed several peaks of mitogenic activity, but none of this could be attributed to epidermal growth factor (EGF)." (PMID 8054274, 1994). "Firstly, we have shown that Detroit 562 cells form tumor spheres when grown in low-adherence dishes and in special medium without serum but with the addition of FGF, EGF, and B27." (PMID 40647457, 2025). "Epidermal growth factor (EGF) and EGFR are expressed in functioning and non-functioning PitNETs, with higher expression in more aggressive tumor subtypes." (PMID 37446128, 2023). "This conclusion is further supported by our observation that stimulation of HDMECs with the pro-angiogenic factors VEGF, EGF, bFGF, IL-6, and TNF-α, which are known to be secreted by tumor cells, has no influence on the expression of endothelial miR-186." (PMID 36845338, 2023). "The molecules secreted by both tumoral and non-tumoral cells, such as VEGF, FGF, EGF, IL6, TNFα, and immune checkpoint molecules, contribute to the crosstalk between the tumor and its microenvironment." (PMID 37958474, 2023). "Moreover, as we noticed, the final outcome could be far from therapeutic in the tumor environment, as the DK-MGhigh cell line evolved to DK-MGextra high, showing a high expression of EGFRvIII in all cells and a lack of response to TGFβ and EGF." (PMID 36292985, 2022). "No imaging of the tumor was possible following the IV injection of the [111In-DTPA, PEG3400-biotinyl]-EGF not bound to the OX26 TfRMAb." (PMID 35745855, 2022). "As a control, the tumor-bearing rats were also injected with the [111In-DTPA, PEG3400-biotinyl]-EGF without attachment to the TfRMAb Trojan horse." (PMID 35745855, 2022). "Although the histology of the original tumor has not been identified, the A-72 cells expressed EGFR, and its growth was promoted by EGF." (PMID 34944112, 2021). "The protocol for the generation of pancreatic organoids included pancreatic normal media that consisted of Noggin, WNT CM, FGF10, EGF, and R-spondin 3, prostaglandin E2 (PGE2) while the tumor media lacked EGF." (PMID 33977021, 2021). "Hepatocyte growth factor (HGF) rather than other growth factors, like epidermal growth factor (EGF), was observed an immediate outburst in the sera of forty HCC patients after tumor resection." (PMID 32206115, 2020). "TMEM97 is regulated by upstream oncogenic signals such as EGF, TGF-β and microRNA in some but not other tumor cells." (PMID 32668577, 2020). "Patient 2: Tumor cells lacking PE in VEGF and EGF, and high PE was detected in more cells with VEGF in the per-section." (PMID 31565199, 2019).
tumor (continued). "Using human ex-vivo GBM slice cultures, it has been found that GBM tumours that have their EGFR gene amplified are more invasive than those that have not, suggesting that EGF signalling stimulates GBM cell migration." (PMID 31601895, 2019). "Compared to GPRC5A wild-type cells, GPRC5A knockout cells have higher levels of activated-STAT3 and STAT3-regulated anti-apoptotic genes, independent of the presence of exogenous epidermal growth factor (EGF), resulting in enhancement of tumor progression." (PMID 30417009, 2018). "Surprisingly, addition of EGF at 50 ng/ml did not further improve viability and proliferation of the EGFR positive tumours in the fragments." (PMID 29861851, 2018). "In JB6 P+ cells, a non-cancerous murine epidermal model for studying tumor promotion, SWT inhibited epidermal growth factor (EGF)-induced neoplastic transformation." (PMID 28335476, 2017). "By instead culturing the cells in FGF-2 (no EGF) we show that the amplification was retained at passage 15 and thus constitute an appropriate model system to study EGFR-amplified pediatric GBM tumor cells." (PMID 28148893, 2017). "Lastly, colony formation was observed with or without the presence of tumor promoters such as TPA and EGF, which resulted in the suppression of colony formation by plasma in terms of both size and quantity." (PMID 28225083, 2017). "Thus, SWT at the non-toxic concentrations 0.0256 and 0.256 mg/mL inhibited EGF-mediated colony formation due to a direct effect on tumor promotion, while the colony inhibitory effect of SWT at 2.56 mg/mL may be attributed to a mixed activity of anti-promotion and cytotoxicity." (PMID 28335476, 2017). "Collective cerebellar tissue infiltration of SHH MB cells was further enhanced by EGF but not HGF, demonstrating differential tumour cell responses to microenvironmental cues." (PMID 28706234, 2017). "Our results confirmed that the EGF-mediated phosphorylation of PIPKIγi2 is required for the dissemination of PDAC cells to distant organs, however does not affect tumor growth." (PMID 28388589, 2017). "Conditioned medium from tumor cell cultures and tumor extracts revealed EGFR binding with TGF immunoreactivity and an absence of EGF activity." (PMID 29056680, 2017). "While MenaINV is known to increase EGF-elicited phosphorylation of cortactin at tyrosine 42143, whether this increase in cortactin tyrosine 421 phosphorylation occurs within specific subcellular compartments, and how this contributes to tumor cell phenotype, have not been determined." (PMID 27824079, 2016). "For in vitro receptor activation, the medium was supplemented with a mixture of the growth factors EGF, HRG, HGF and IGF to compensate for the absence of tumor–stroma interactions." (PMID 27578890, 2016). "Here, we show that EGF stimulation promotes MUC1 cleavage, which is both necessary and sufficient to initiate tumor cell metastasis but has no impact on primary tumor growth." (PMID 22586492, 2012). "Using in vitro analyses of the tumor-derived cell lines, we have found no significant physical or functional interaction between EGFR (erbB1) and erbB2 in the presence of EGF (data not shown)." (PMID 16168116, 2005). "For the borderline tumours, four of six (67%) expressed EGF receptor mRNA, 1/6 (17%) expressed TGF-alpha mRNA and none expressed EGF mRNA." (PMID 8562334, 1996). "A key future direction is to explore if EGF/STAT3 signaling can ectopically induce SOX11 in non-tumorigenic cells, and if so, whether this prompts TWIST expression and a tumor-like phenotype." (PMID 41511366, 2026). "In order to exclude the impact of EGF and CXCL11 on anlotinib-induced anti-migrating ability, we added rhCXCL11 and rhEGF to tumor cell with or without anlotinib treatment and found that invasion and migration of ATC cells could hardly be influenced." (PMID 37283515, 2023).
tumor (continued). "Because HGF, but not EGF, significantly alleviated the suppressive effect of Cfd-KO mADSCs on tumorsphere formation in vitro, we evaluated the effect of HGF to alleviate the suppressive effect of Cfd-KO mADSCs on tumor formation in vivo." (PMID 34439392, 2021). "EGFR nuclear translocation positively correlates with features of tumor aggressiveness: A549 and GLC82 cells expressing wild type EGFR increase their clonogenicity and proliferation in response to PGE2 or EGF in contrast to cells expressing a mutant EGFR lacking its nuclear localization sequence." (PMID 28415726, 2017). "In addition, HVS caused a dose-dependent inhibition of HGF-induced, but not epidermal growth factor (EGF)-induced, cell scattering in addition to HGF-mediated migration, invasion, and 3-dimensional (3D) proliferation of tumor cell spheroids." (PMID 27086914, 2016). "Together, our results show that unlike in some tumors, where Spry may mediate tumor suppression, Spry1 plays a selective role in at least a subset of TNBC to promote the malignant phenotype via enhancing EGF-mediated mesenchymal phenotype." (PMID 26976794, 2016). "Interestingly, also a number of oncogenes is up regulated by E2 (MERTK, RET and its ligand ARTN), and several (putative) tumor suppressor genes are down regulated by E2 (BLNK, LATS2, RPRM) that are not, or less, regulated by EGF." (PMID 24758408, 2014). "Levels of EGF and TGF-alpha did not correlate with levels of EGF receptor (EGFR) as determined by a radioligand binding method but levels of TGF-alpha > 10 ng gm-1 of tumour tissue did correlate with EGFR positivity defined using immunohistochemistry." (PMID 8605103, 1996). "Using an in vitro model system representing various stages of breast oncogenesis, LEA.92 was detected on normal or immortalised mammary epithelial cell (MEC) lines which were dependent on epidermal growth factor (EGF) and anchorage formation for growth and non-tumorigenic in nude mice." (PMID 8123470, 1994). "Moreover, TGF- β is not the sole inducer of EMT, and in the tumor microenvironment, there are other paracrine signaling pathways such as WNT pathway, NOTCH signaling, and mitogenic growth factor such as EGF and FGF-mediated activation pathways acting in combination to induce an EMT program." (PMID 34912796, 2021). "Moreover, the 60 s kINPen plasma treatment, which reduced absolute lesion and tumor sizes significantly, was the only treatment not showing a reduction in ACVR1B, ACVR2A, CSF1, EGF, EGFR, IL15, and IL6RA when compared to all other treatments in the high dose DBP group." (PMID 34667240, 2021). "Furthermore, tumour cells and non-malignant stromal cells secrete different growth factors such as TGF-β1, EGF, vascular endothelial growth factor (VEGF), FGF, TNF-α, IL-1β, and IL-6 that promote CAF trans-differentiation and activation, contributing to a pro-inflammatory profile and carcinogenesis." (PMID 34830058, 2021). "The receptors expressed by the tumors developed in vivo were not assessed, so EGF-conjugated GNPs were used as a potential more targeted tool for tumor cells in comparison to healthy cells, based on the increased expression of EGFR in tumor cells reported in literature." (PMID 33353068, 2020). "Moreover, EGF-conjugated HAOA-coated nanoparticles did not markedly decrease HaCaT cell viability, showing high biocompatibility with healthy tissues, and were able to enter the EGFR-overexpressing tumor cell line A549, by different internalization mechanisms." (PMID 27788212, 2016). "Augmented EGF signaling to Rho mediated by clustered EGFR may have relevance to chemotaxis and directed motility of nonadherent (circulating) or less adherent (migrating) tumor cells." (PMID 19470173, 2009).
cancer (1,978 papers, 1990 to 2026). A tumor composed of atypical neoplastic, often pleomorphic cells that invade other tissues. "In vitro experiments demonstrated that SERPINE1 promoted GC cell proliferation and invasion, and its expression was enhanced by cancer-associated fibroblasts (CAFs) through the EGF-ERBB signaling pathway." (PMID 41551463, 2026). "ACAP4 regulates membrane–cytoskeletal dynamics in response to a variety of stimuli such as EGF and histamine and is implicated in cancer cell migration and invasion." (PMID 40082743, 2025). "Affected kinases were significantly enriched in cancer-associated pathways, including insulin signaling, EGF–EGFR signaling, PI3K/AKT signaling, and the PD-L1/PD-1 immune checkpoint axis." (PMID 40832614, 2025). "For example, the ligand EGF in cancer epithelial cells is significantly associated with the receptors ERBB2 (P value = 0.009) and EGFR (P value = 0) in CAFs, suggesting a potential signaling cascade from the former to the latter." (PMID 38279156, 2024). "It releases active forms of the primary inflammatory cytokine tumor necrosis factor (TNF) and cancer-implicated epidermal growth factor (EGF) family growth factors." (PMID 38781971, 2024). "We also found little evidence that several putative key inflammatory mediators in cancer development (e.g., epidermal growth factor, interleukin-6 receptor, interleukin-8) were associated with cancer risk." (PMID 38301482, 2024). "In oncology, while EGF is essential for normal cellular functions, its overexpression or dysregulation is associated with various cancers." (PMID 39064802, 2024). "As the cancer progressed, ctDNA analysis showed the appearance of an epidermal growth factor (EGFR) mutation in the plasma samples." (PMID 39272653, 2024). "The overexpression of EGFR in a number of tumors promotes the susceptibility of cancer cells to small concentrations of EGF." (PMID 38338748, 2024). "Although EGF has been mostly associated with cancer, in studies mostly focused on EGFR activation, this molecule has other potential functions." (PMID 39110087, 2024). "In particular, the significance of EGFR signaling cascade in cancer progression has been drawing substantial attention; the EGF stimulation system for growth regulation is implicated in both normal and neoplastic cell proliferation." (PMID 36979595, 2023). "A second type, defined as Luminal B, is positive for hormone receptors (ER+, PR+), but also overexpresses the Her2 (Her2+) receptor, a receptor for epidermal growth factor (EGF) which is associated with cancer aggressiveness." (PMID 37892432, 2023). "In this work, we investigate which downstream kinase-associated pathway is activated by EGF to spatially regulate glucosome dynamics and thus functionally control glucose flux in cancer cells." (PMID 35122791, 2022). "It has been reported that EGFR mutation is involved in the RANKL pathway and EGF signals are involved in bone metastasis of many cancers." (PMID 36581856, 2022). "Compared with free DOX, EGF@DOX-NPs exhibited superior cytotoxic against cancer cells both in vitro and in vivo and was associated with minimal side effects." (PMID 35156493, 2022). "Many cytotoxic compounds have been covalently linked to EGF using the polypeptide as a vehicle for the delivery of these agents to a broad spectrum of cancer cells." (PMID 35213974, 2022). "The EGF targeting of the AF488-EGFHi-λ was associated with a delay in the association of phages with the cancer spheroid, which only became significant and clearly observable after 8 h." (PMID 36591314, 2022). "The human FAT genes encode large transmembrane proteins with Cadherin repeats, epidermal growth factor (EGF)-like domains, and Laminin G-like domains, which frequently mutated across multiple cancer types." (PMID 35836939, 2022).